RN7SL260P (RNA, 7SL, cytoplasmic 260, pseudogene)
Gene: Miscellaneous RNA gene on chromosome 8 (142,247,585 to 142,247,866, reverse strand). Ensembl gene ENSG00000253602.
Homologues: Orthologues: chimpanzee Metazoa_SRP (98% identical), macaque Metazoa_SRP (88% identical). Paralogues in human: RN7SL1 (87% identical), RN7SL3 (86% identical), RN7SL2 (86% identical), RN7SL448P (83% identical), RN7SL230P (82% identical), RN7SL126P (82% identical), RN7SL45P (82% identical), RN7SL664P (82% identical), Metazoa_SRP (82% identical), RN7SL220P (82% identical), RN7SL278P (82% identical), RN7SL357P (82% identical), and 704 more.